MYBPC3 (myosin binding protein C3)
Diseases named in the same sentence as MYBPC3 in open-access papers (continued):
Sharing a sentence is not in itself a finding about the gene and the disease.
familial cardiomyopathies (2 papers, 2011 to 2022). "HCM is a hereditary cardiomyopathy characterized by ventricular asymmetric hypertrophy, with mutations in the MYBPC3 gene detected in 40% of all FHCM cases." (PMID 35717150, 2022). "Three MYH6 mutations were novel and two (one MYH6 and one MYBPC3) were previously found in patients with familial cardiomyopathies." (PMID 22194935, 2011).
muscular dystrophy (2 papers, 2023 to 2025). Muscular dystrophy (MD) refers to a group of more than 30 genetic diseases characterized by progressive weakness and degeneration of the skeletal muscles that control movement. "Consistent implication of MYBPC3, CSRP3, CAV3, TCAP, and TTN across multiple pathways highlights convergent mechanisms, while moderate enrichment of muscular dystrophy pathways (involving CAV3 and TTN) further suggests overlapping pathophysiological networks." (PMID 41153379, 2025).
Obesity (2 papers, 2018 to 2023). Accumulation of substantial excess body fat. "More studies are warranted to clarify the potential mechanism underlying the associations between MYBPC3 and obesity." (PMID 29854750, 2018).
Tetralogy of Fallot (2 papers, 2021 to 2022). A congenital cardiac malformation comprising pulmonary stenosis, overriding aorta, ventricular septum defect, and right ventricular hypertrophy. "Finally, an interesting finding after NGS analysis is the presence of the likely pathogenic variant p.(Arg726Cys) in the MYBPC3 gene in two unrelated patients, one exhibited noncompaction cardiomyopathy and the other Tetralogy of Fallot (ToF) as part of a phenotype with MCA." (PMID 35885957, 2022).
Alzheimer disease (1 paper, 2021). A progressive, neurodegenerative disease characterized by loss of function and death of nerve cells in several areas of the brain leading to loss of cognitive function such as memory and language. "STX3, one of the novel TWAS significant genes was dropped after conditional analysis along with three of the genes in Alzheimer’s disease risk loci: FNBP4, MYBPC3 and MS4A6A." (PMID 33959712, 2021).
arrhythmogenic right ventricular dysplasia type 5 (1 paper, 2023). "In our study, TTN DCM type 1G, KCNQ1 LQTS type 1, MYBPC3 HCM type 4, and TMEM43 arrhythmogenic right ventricular dysplasia type 5 were the most frequent CVD, and MSH6 Lynch syndrome and PALB2 HBC were the most frequent CPC among ACMG SFs." (PMID 36635046, 2023).
cardiac conduction disease (1 paper, 2024). "In a large meta-analysis of 31 studies with 6123 HCM patients, MYBPC3 variant carriers (20% of all HCM patients) had less cardiac conduction disease, less ventricular arrythmia and less HTx (present in 15%, 20% and 0.6% of all MYBPC3 variant carriers respectively) compared to MYH7 variant carriers." (PMID 38836037, 2024).
Emery-Dreifuss muscular dystrophy (1 paper, 2017). Emery-Dreifuss muscular dystrophy (EDMD) is characterized by muscular weakness and atrophy, with early joint contractures and cardiomyopathy. "Furthermore, manifestation of clinical symptoms of pathogenic mutations is more likely to appear with increasing age of individual which, again, was showed for HCM and MYBPC3 mutations or Emery-Dreifuss muscular dystrophy and LMNA." (PMID 28045975, 2017).
endothelial dysfunction (1 paper, 2026). In vascular diseases, endothelial dysfunction is a systemic pathological state of the endothelium (the inner lining of blood vessels) and can be broadly defined as an imbalance between vasodilating and vasoconstricting substances produced by (or acting on) the endothelium. "Higher MYBPC3 was most prognostic in HFrEF while higher ANGPT2 and IGFBP7 (endothelial dysfunction and oxidative stress) in HFpEF." (PMID 41711204, 2026).
myopia (1 paper, 2024). "Because the retina is a neural tissue, the expression of numerous genes linked to cardiac muscle (MYBPC3, ACTC1, MYL3, MYH7, MYH7B) or to skeletal muscle (MYL1, SMYD1, TNNI2, MYH1B, ACTA1, TNNT3) presents a conundrum for explaining a mechanism for myopia progression." (PMID 39028695, 2024).
protein deficiency (1 paper, 2023). "The molecular pathomechanism underlying HCM associated with MYBPC3 mutations has often been identified in cMyBP-C protein deficiency." (PMID 36744470, 2023).
Sinus bradycardia (1 paper, 2024). Bradycardia related to a mean resting sinus rate of less than 50 beats per minute. "Still, some gene mutations, such as NOTCH genes, ACTC1, MYH7, MYBPC3, TTN, and HCN4, among others, have been implicated with the HCN4 gene responsible for sinus bradycardia in some patients." (PMID 39677872, 2024).
heart disease (22 papers, 2018 to 2025). "There are no reports describing a specific phenotype of the homozygous MYBPC3 c.1224-52 G>A (IVS13-52 G>A) variant in pediatric patients with cardiac disease." (PMID 36980931, 2023). "Thirty-three of the fifty-nine ICD-9 codes and fifty-eight of the 104 ICD-10 codes are linked to heart disease showing their prevalence and impact on patients with a genetic mutation in the MYBPC3 gene." (PMID 37195695, 2023). "The protein product of PDLIM3 is predicted to interact with the protein products of several other genes that are linked with heart disease, including MYBPC3, ACTN2, and CAV3." (PMID 32013268, 2020). "Mutations of Jp2, Tnni3, and Mybpc3 are closely relevant to the heart diseases." (PMID 35242109, 2022). "Recently, several variants in the sarcomere genes such as Myosin Heavy Chain 7 (MYH7) and Myosin Binding Protein C3 (MYBPC3) have been identified in patients with heart diseases." (PMID 35872890, 2022). "Future studies are warranted to establish this link (cause-consequence) between reduced cMyBP-C protein levels, increased α-tubulin acetylation and cardiomyocyte contractile function and hypertrophy that may underlie initiation and progression of cardiac disease in MYBPC3 mutation carriers." (PMID 31323898, 2019). "According to world literature, the genes mainly involved are MHY7 and MYBPC3, although variants have been found in more than 50 genes related to heart disease and sudden death, and to our knowledge there are no studies in the Mexican population." (PMID 37498360, 2023). "Thus, it remains unclear if MYBPC3 p.Gly148Arg alone leads to a cardiac phenotype especially considering the pedigree which is free of any cardiac diseases." (PMID 31293105, 2019). "MYBPC3, TTN and SCN5A are established cardiac disease genes, but SH3BGR and HMCN2 are not." (PMID 31641117, 2019).
cardiovascular diseases (6 papers, 2020 to 2025).
genetic disorder (3 papers, 2020 to 2021). "Neonatal hypertrophic cardiomyopathy is a genetic disorder caused by mutations in MYBPC3 gene (p.Glu258Lys and IVS25-1G>A)." (PMID 34722422, 2021). "HCM is a recognized genetic disorder most often caused by mutations involving myosin-binding protein C (MYBPC3) and β-myosin heavy chain (MYH7) which are responsible for approximately three-quarters of the identified mutations." (PMID 33297970, 2020).
infection (2 papers, 2019 to 2025). The state of being infected such as from the introduction of a foreign agent such as serum, vaccine, antigenic substance or organism. "Relative to EV cells, the abundance of MyBPC3 mRNA was determined in both WT and P459fs cells, indicating the success of stable infection." (PMID 40083819, 2025).
mitochondrial disease (2 papers, 2016 to 2023). "Defects in sarcomere genes, such as MYH7, MYBPC3, TNNT2, TPM1, ACTC1, and TTN have been reported as causative for LVNC and LVNC is also commonly associated with mitochondrial diseases." (PMID 37186429, 2023).
neurological diseases (1 paper, 2021). "Besides that, in this LD block, several variants act as eQTLs/sQTLs in the brain and whole blood, altering the expression of many genes already related to LOAD or other neurological diseases in human or animal studies, such as CELF1 itself, MADD, MYBPC3, NR1H3, NUP160, SPI1, and TOMM40." (PMID 34291080, 2021).
MYBPC3 also shares sentences with these, for which no sentence is quoted: familial hypertrophic cardiomyopathy (9 papers); hypertrophy (6); long QT syndrome (6); Brugada syndrome (5); myopathy (5); familial hypercholesterolemia (4); ischemic heart disease (3); myocarditis (3); cancer (2); chronic kidney disease (2); congenital heart disease (2); ischemia (2); ketoacidosis (2); Malignant hyperthermia (2); myocardial ischemia (2); restrictive cardiomyopathy (2); ventricular fibrillation (2); Ventricular hypertrophy (2); ventricular septal defect (2); acute myeloid leukemia (1); acute myocardial infarction (1); advanced heart failure (1); amyloidosis (1); asymmetrical septal hypertrophy (1); Autoimmunity (1); autosomal dominant disease (1); Barth syndrome (1); catecholaminergic polymorphic ventricular tachycardia (1); channelopathy of (1); chronic respiratory failure (1).
A further 50 diseases each share a sentence with MYBPC3 in 1 paper.